IL10 (interleukin 10)
Diseases named in the same sentence as IL10 in open-access papers (continued):
Sharing a sentence is not in itself a finding about the gene and the disease.
rheumatoid arthritis (continued). "Additionally, HSP60 has been shown to prevent inflammation-induced cell death in rheumatoid arthritis (RA) by promoting the secretion of anti-inflammatory cytokines IL-4 and IL-10 at the site of inflammation in the bone." (PMID 38791521, 2024). "Such a mechanism, with resistance to IL-10-mediated inhibition of IFN-γ production, has previously been described in patients with active rheumatoid arthritis (RA)." (PMID 36752779, 2023). "In the context of rheumatoid arthritis, atopic dermatitis, and IBD, the administration of IRT5 increased the levels of IL-10, TGF-β, and IDO in DCs, leading to the induction of Tregs139." (PMID 38087439, 2023). "In the rheumatoid arthritis mouse model, MDSC-derived IL-10 helps in the generation of Tregs but attenuates inflammation." (PMID 35720398, 2022). "Exposure of PBMC from both healthy donors and patients with rheumatoid arthritis to CD40L and CpG led to an increased number of IL-10–producing Bregs." (PMID 36052064, 2022). "In rheumatoid arthritis, CCR1 regulates the expression of TNFα and IL-10, and is therefore an efficient therapeutic target." (PMID 33509198, 2021). "For example, IL-10 positive M2(IL-10)-like macrophages have been found in the lining layer of the synovium in rheumatoid arthritis (RA) and, more prominently, in spondylarthritis (SpA), whilst the sub-lining layers consisted more of a heterogenous M1/M2-like pattern." (PMID 32787920, 2020). "However, while IL-10 based therapy is attractive, further work will be required in order to perfect the stability and delivery of the peptide to the heart, as trials for its use in diseases such as rheumatoid arthritis and Crohn’s disease have found only modest improvements." (PMID 33192505, 2020). "Accordingly, patients deficient in CD46 cannot generate Th1 responses and suffer from recurrent infections, while dysregulation in this CD46/IL-2R crosstalk leads to a reduced IL-10 switching and hyperactive Th1 responses in rheumatoid arthritis (RA) and multiple sclerosis." (PMID 30700717, 2019). "Ananalysis of the potential precursors of IL-10+ B cells(CD19+TGF-β+ and CD19+FOXP3+populations) showed a decrease in the number of both populations in patientswith rheumatoid arthritis." (PMID 30397522, 2018). "Protective effects on the clinical and immunopathological features of rheumatoid arthritis by reducing serum IL-17 and increasing IFN-r and IL-10." (PMID 29163443, 2017). "Several studies in murine models of rheumatoid arthritis have demonstrated the efficacy of TNF-, IL-10-, and dexamethasone-treated TolDCs to treat collagen-induced arthritis, an experimental model for inflammatory joint diseases." (PMID 26539197, 2015). "Consistent with this hypothesis, patients with inflammatory diseases (SLE, rheumatoid arthritis, Sjögren’s syndrome, autoimmune vesiculobullous skin disease, and multiple sclerosis) have shown significantly increased frequencies and absolute numbers of IL-10-producing B cells." (PMID 22927996, 2012). "Following the encouraging preclinical results presented in this paper, clinical trials with F8-IL10 will now elucidate the therapeutic potential of this product and whether the targeted delivery of IL10 potentiates the anti-arthritic action of the cytokine in rheumatoid arthritis patients." (PMID 19781067, 2009). "Additionally, it remains to be clarified whether IL-10 decrease is a specific outcome of ESW treatment or mediated by TNF-alpha reduction since it has been shown that TNF-alpha up-regulates IL-10 expression in rheumatoid arthritis synovitis." (PMID 18237379, 2008). "Similarly, in chronic inflammatory conditions like rheumatoid arthritis and COPD, IL-10 helps regulate immune responses and promote tissue repair." (PMID 40076949, 2025). "IL-10 has been shown to alleviate CIPN and rheumatoid arthritis." (PMID 36774519, 2023).
rheumatoid arthritis (continued). "Furthermore, overexpression of IL-6, IL-10, IL-17, and TNF-α, among others, is important in the pathogenesis of SLE, polymyositis (PM), dermatomyositis (DM) and rheumatoid arthritis (RA) and is significantly related to disease activity." (PMID 33882880, 2021). "Interestingly, untreated rheumatoid arthritis, systemic sclerosis, and SLE patients had lower IL10 production by Breg cells than treated patients." (PMID 32775471, 2020). "Estrogen in larger quantities can decrease inflammation by increasing regulatory cytokines such as interleukin-10 (IL-10) and transforming growth factor-β (TGFB), which is why it is believed to act as a protective mechanism against rheumatoid arthritis and Sjogren’s syndrome." (PMID 32542149, 2020). "Tofacitinib is used to treat rheumatoid arthritis and it is known that tofacitinib can increase the expression of pro-inflammatory mediators, including PGE2, in macrophages by acting inhibitory on the expression of anti-inflammatory IL-10." (PMID 32435199, 2020). "In a recent publication it was reported that supplementation with probiotics improved disease activity and the inflammatory status in patients with rheumatoid arthritis (RA) and the administration of a probiotic mixture exerted a therapeutic effect on EAE that was mediated by IL-10." (PMID 24919069, 2014). "In rheumatoid arthritis, patients significantly altered serum cytokines, reducing TNF-α, IL-15, and RANTES (Regulated on activation, normal T expressed and secreted), while increasing IL-10, which correlated with clinical improvement, especially in treatment responders." (PMID 41044647, 2025). "The parasitic worm-derived immunomodulator, ES-62 rescues defective levels of IL-10-producing regulatory B cells (Bregs) and suppresses chronic Th1/Th17-driven inflammation to protect against joint destruction in the mouse collagen-induced arthritis (CIA) model of rheumatoid arthritis." (PMID 38500783, 2024). "In the model of rheumatoid arthritis (RA), ENO1 induces early production of pro-inflammatory cytokines and chemokines but delays production of IL-10 to activate the innate immune system." (PMID 36614179, 2023). "Tangeretin also had therapeutic effects on rheumatoid arthritis (RA), it suppressed arthritis severity in rats with collagen-induced RA, decreased the production of MDA and pro-inflammatory factors but enhanced the expression of IL-10 and Nrf2-related antioxidant enzymes." (PMID 37767395, 2023). "Butyrate supplementation, a metabolite produced by the microbiota, promotes an increased frequency of IL-10+ Bregs in rheumatoid arthritis patients, and mice lacking IL-10 producing B cells do not experience the same disease suppression following butyrate treatment." (PMID 37600781, 2023). "For example, in rheumatoid arthritis BiP at the cell surface can stimulate tumor necrosis factor (TNF) production to promote inflammation, but BiP can also act as an antigen to stimulate CD8-positive T cells leading to increased production of the anti-inflammatory cytokine IL-10." (PMID 34268295, 2021). "Moreover, the serum levels of pro-inflammatory cytokines that persist in rheumatoid arthritis including interleukin IL-1β, IL-6 and IL-10 were decreased, although the level changes had not reached statistical significance." (PMID 27658047, 2016). "Interestingly the cytokine profile in the skin of patients with chronic urticaria mimics that found in patients with psoriasis, psoriatic arthritis, and rheumatoid arthritis with increased expression of TNF-alpha and IL-10 and decreased expression of IL-2 and interferon gamma." (PMID 24167521, 2013). "Similarly, cytokine-stimulated T lymphocytes, which are comparable to rheumatoid arthritis synovium T lymphocytes, fail to trigger IL-10 production in monocytes, but not in M-CSF-differentiated macrophages." (PMID 20195532, 2010).
rheumatoid arthritis (continued). "Also, HSP40 has been shown to exert immunoregulatory function in patients with rheumatoid arthritis (RA), where HSP40 represses the proliferation of CD4+ and CD8+ T cells and stimulates the secretion of IL-10 by PBMCs." (PMID 33023034, 2020). "Thus, the RA group showed an increased percentage of CCR4+ Tregs and a higher production of IL-10 and TGF-β, which may indicate a compensatory activated state of Treg cells in rheumatoid arthritis that could be caused by physiological mechanisms or the medications applied for treatment." (PMID 33809452, 2021).
parasitemia (259 papers, 2005 to 2026). "Previous exposure to the parasite can influence the IL-6 and IL-10 response, which is associated with increased parasitemia, reduced maternal weight gain and premature delivery." (PMID 39495782, 2024). "Parasite density was the principal predictor of the cytokine levels, as parasitemia positively associated with IL‐10, GM‐CSF, IL‐6, IL‐1β, IFN‐ɣ, and TNF‐α, but negatively associated with IL‐3 and TGF‐β." (PMID 39240033, 2024). "Consistent with the previous findings, Th1 and Tr1 cells are implicated as being the predominant sources of IL-10 during chronic viral and parasitic infections." (PMID 38317180, 2024). "Previous studies reported that serum IL-10 levels were positively associated with parasitemia in patients infected with P. falciparum, P. knowlesi, and P. vivax." (PMID 36668942, 2023). "Loss of Bhlhe40 expression in mice results in higher Il10 expression, higher peak parasitemia, and a delay in parasite clearance." (PMID 37843306, 2023). "Surprisingly, in our study IL-6 and IL-10 were moderately associated with temperature and only Il-6 was correlated with parasitemia load." (PMID 36787308, 2023). "Higher IL-10 was significantly associated with higher parasitemia (R = 0.32 [0.16–0.46]; P = 0.0001)." (PMID 37365194, 2023). "Given its association with alternative macrophage activation and parasitic infection, we next considered the potential role of IL-10 in IL-4/13 induced macrophage innate memory responses." (PMID 36173104, 2022). "In a model of Trichuris muris-infected mice, IL-10 was shown to play a key role in controlling the inflammation caused by parasite infection and in the establishment of long-term infection." (PMID 32894178, 2020). "Compared to WT mice, TgAlbCre-IL10-/- mice exhibited a similar parasitemia, anemia and weight loss profile and had a similar survival profile in this model." (PMID 32012211, 2020). "Here, in a large cohort of children aged 6 months to 10 years, we found that recurrent and/or high-density Pf parasitemia was associated with an IL10-dominant CD4 T-cell phenotype, particularly in younger children." (PMID 29097996, 2017). "T regulatory cells (Treg) and its typical cytokine IL-10 mainly exert their suppressive effects on the development of Th2 allergic responses, which are significantly susceptible to parasitic infections." (PMID 28651566, 2017). "IL-10 was also associated with high levels of parasitemia of P. falciparum in patients with CM and non-CM55." (PMID 27554340, 2016). "All of the cytokines were negatively associated with parasitemia, with the exception of IL-10, TNF-α, and IL-6." (PMID 27418744, 2016). "The Pearson correlations, used to load the mediation model, showed an inverse association between IL-4, IL-12, and IFN-γ, and parasitemia and a positive correlation between IL-10 and parasitemia." (PMID 27418744, 2016). "Parasitemia was significantly correlated with the following cytokines, in order of strength of association: IL-10, IL-12, TNF-α, IFN-γ, IL-1β, IL-6, IL-5, IL-2, IL-4, and IL-7." (PMID 27418744, 2016). "T cells, in particular IFN-γ-producing T cells, have been implicated in orchestrating the control of peripheral parasitemia in both models, whereas IL-10 producing T cells have been shown to exacerbate P. yoelii XNL parasitemia." (PMID 25996913, 2015). "The present study is, to our knowledge, the first examining an association between STH infections and IL-10, not only in Honduras but in the Central American region, an area endemic for many parasitic infections including STH." (PMID 25888883, 2015). "We observed in our previous clinical study that IL-10 levels were very closely associated with parasitemia." (PMID 24520384, 2014). "A recent study has demonstrated that IL-10 production from B cells is required for susceptibility to parasitic infection." (PMID 23071588, 2012).
parasitemia (continued). "In line with this, we found that depletion of CD25+ T cells by anti-CD25 mAb led to a significant increase in serum levels of IFN-γ and IL-10, and this was associated with increased prepatent period and lower parasitemia in infected mice." (PMID 22860150, 2012). "IL-10 plays an important role in developing susceptibility to parasite infection by inhibiting cell-mediated immunity and inflammation." (PMID 23071588, 2012). "IgG1 and IgG3 production although occasionally related to a Th1 human response, has been consistently linked in human parasitic infections to IL-10." (PMID 16364177, 2005). "Furthermore, the Granger Causality Test revealed that IL-10 was the only cytokine statistically proven (p < 0.05) caused by parasitemia." (PMID 40743218, 2025). "Only IL-10 was significantly associated with parasitemia (R = 0.32 [0.16–0.46]; P = 0.0001)." (PMID 37365194, 2023). "Higher IL-10 levels were significantly associated with higher parasitemia." (PMID 37365194, 2023). "High levels of IL-10 are associated with a reduced ability to eliminate parasitemia." (PMID 37628675, 2023). "The immunosuppressive role of IL-10, upregulated by saliva, was shown to exacerbate the infection and disease; early IL-10 expression was associated with increased T regulatory cell proliferation, suppression of Th1 cytokines, as well as the increase of the parasitemia and mortality." (PMID 34035796, 2021). "B cell-deficient mice developed significantly lower levels of parasitemia after B. microti infection and exhibited lower levels of serum IL-10 compared to wild-type mice, suggesting that IL-10-producing B cells may play a role in susceptibility to B. microti." (PMID 33233869, 2020). "Additionally, IL-10 acts as an anti-inflammatory cytokine preventing the pathology associated with parasite infections, down-regulating the host immune response." (PMID 25811778, 2015). "For P. chabaudi infection, the co-infected Il10−/− mice had lower P. yoelii parasitemia, suggesting that part of the effect of IL-10 deficiency on inflammatory responses may be an indirect effect of reduced parasite infection." (PMID 24787713, 2014). "Animal studies have suggested that IL-10 may play a regulatory role that modulates susceptibility to parasite infection." (PMID 20706538, 2010). "Animal studies have suggested that IL-10 may play a regulatory role during parasitic infection that modulates susceptibility." (PMID 18230163, 2008). "Moreover, high levels of IL-10 were associated with a reduced ability to eliminate parasitemia." (PMID 37628675, 2023). "Furthermore, cytokines, IL-6, IL-10, and IL-11 stimulate humoral immune responses during parasite infection that could cause differences in expression level of immunoglobulins and humoral immune responses in both fish species during PKD pathogenesis." (PMID 25563603, 2015). "With regard to previous studies and the present results, we can suggest that IFN-γ, acting in synergy with IL-10, could be associated to events leading to the predominant IgG3 production as previously observed during others parasitic infections [F. Remoue, unpublished data]." (PMID 20856680, 2010). "Males develop higher Th1 responses, including elevated IFN synthesis, whereas females exhibit higher IL‐10 production during the early phase of parasitic infections." (PMID 41523753, 2026). "During the initial weeks of infection, macrophage activation through cytokines such as IFN-γ is primarily responsible for controlling parasitemia while IL-10 plays a critical role in preventing excessive tissue damage caused by an overactive immune response." (PMID 41007442, 2025). "Following parasite infection, IL-10 levels decreased in the untreated group compared to the uninfected/untreated control (** p < 0.01) and remained unchanged in the treated groups." (PMID 40871442, 2025). "An exciting aspect of this study is the simultaneous correlation between cytokine expression, mainly IFN-γ and IL-10, and parasitemia." (PMID 40743218, 2025).